TLR4 (toll like receptor 4)
Diseases named in the same sentence as TLR4 in open-access papers (continued):
Sharing a sentence is not in itself a finding about the gene and the disease.
colorectal cancer (continued). "Furthermore, TLR4 overexpression increased HIF1α and VEGF levels in colorectal cancer cells, while TLR4 knockout led to significant reduction in their levels." (PMID 35955525, 2022). "Few research studies have investigated the relationship between Desulfovibrionaceae and CRC, however, many studies reported that it is an endotoxin-producer, endotoxin can promote colorectal cancer cells adhesion and invasion through the regulation of the TLR4/NF-κB pathway." (PMID 35447933, 2022). "Additionally, it is reported that β-catenin signalling can be triggered in colorectal cancer via a TLR4/P-PAK1 cascade." (PMID 35801728, 2022). "Bmi-1 may also regulate the TLR4/MD2/MyD88 complex-mediated NF-κB signaling pathway to participate in colorectal cancer cell EMT." (PMID 35897796, 2022). "For instance, microarray analyses identified that miR-4793-3p was upregulated in the hepatic metastasis of colorectal cancer tissue samples and in necrotizing enterocolitis, which may be involved in the TLR4 pathway." (PMID 34354043, 2021). "Also, in colorectal cancers, nuclear factor-kB (NF-kB) activate through lipopolysaccharide (LPS) that binds to the Toll-like receptor 4 (TLR4)." (PMID 33105724, 2020). "Thus, Fusobacterium nucleatum–induced proliferation of colorectal cancer cells and tumor development activate TLR4 and RASA1 signaling." (PMID 32422978, 2020). "TLR4 turned out to be the dominant TLR in colorectal cancer tissues." (PMID 32050430, 2020). "AT-I had the anti-tumor effects against many cancers, such as colorectal cancer, non-small cell lung cancer and melanoma, and it also had a binding site similar to LPS and served as a novel TLR4-antagonizing agent." (PMID 33363472, 2020). "Hence, TLR4 has become a target in colorectal cancer therapy due to its critical roles in promoting cancer cell survival, development and progression." (PMID 32322173, 2020). "Moreover, observed discrepancies in responsiveness to LPS between colon carcinoma and primary epithelial cells can be further explained by previous studies describing upregulation of TLR4 in colorectal cancer, including HT-29 cells." (PMID 32314963, 2020). "However, F. nucleatum promotes colorectal cancer cell (CRC) line proliferation by modulating the E-cadherin/β-catenin signaling pathway or activating Toll-like receptor 4 signaling to nuclear factor-kB." (PMID 31921705, 2019). "It is therefore possible to hypothesize that colorectal cancer cells are more sensitive to the activation of TLR4." (PMID 31186484, 2019). "In addition, TLR4-signaling engagement promotes the adhesiveness and metastatic capacity of colorectal cancer." (PMID 29928275, 2018). "TLR4 has been detected in both gastric and colorectal cancer." (PMID 27191981, 2016). "Colorectal cancer (CRC) is aggressive and associated with TLR4-MD-2 signaling." (PMID 27409669, 2016). "The results indicated that HCMV infection may be associated with colorectal cancer and adenoma and inflammatory responses may be mediated by the TLR2 or TLR4 signaling pathways." (PMID 25435993, 2015). "HCMV infection was found to correlate with the expression of TLR2 and TLR4 in colorectal cancer." (PMID 25435993, 2015). "We also found that TLR4 expression on colorectal cancer cells was up-regulated by 5-FU treatment." (PMID 24250621, 2013). "Inhibition of LPS-induced TLR4 signaling could improve therapeutic outcomes by preventing cancer metastasis during the perioperative period of colorectal cancer resection." (PMID 22583829, 2012). "However, the impact of bacterial lipopolysaccharide (LPS) binding to Toll-like receptor 4 (TLR4) on chemokine receptors in human colorectal carcinoma cells still remains to be elucidated." (PMID 22180778, 2011). "Furthermore, it was demonstrated that concomitant expression of the three molecules TLR4, MD-2 and CXCR7 is associated with increased carcinoma growth and metastasis potential in human colorectal carcinoma." (PMID 22180778, 2011).
colorectal cancer (continued). "Moreover, the differences in expression of TLR4 and MD-2 between normal colorectal tissues and colorectal carcinoma tissues were all found to be statistically significant." (PMID 22180778, 2011). "Here we show enhanced expression of TLR-4 on cells of the epithelial and stromal tissue compartment as well as players in the inflammatory and angiogenic pathways are strongly increased during colorectal cancer progression." (PMID 21059221, 2010). "Additionally, a similar study developed a multi-epitope peptide based on neoantigens that targets TLR4/MD2 as a possible vaccine against colorectal cancer, demonstrating its reliance on TLR4 binding and capacity to trigger powerful immune responses against colorectal cancer antigens." (PMID 40453095, 2025). "Importantly, the pro-tumorigenic role of LPS/TLR4/NF-κB signaling extends beyond colorectal cancer, with demonstrated significance in bone cancer, hepatocellular carcinoma, and ovarian cancer, highlighting its broad relevance as a therapeutic target across malignancies." (PMID 41235258, 2025). "The p38 MAPK pathway may be activated when RETN attaches to TLR4 on colorectal cancer cells." (PMID 39839775, 2024). "Besides that, aspirin also lead to down-regulation of TLR4 expression in colorectal cancer cells." (PMID 36647071, 2023). "Yu and colleagues have also shown that, in colorectal cancer models, Fusobacterium nucleatum may activate TLR4 and MyD88 immune signalling pathways, as well as downregulation of specific microRNAs in order to activate the autophagy pathway and reduce cell apoptosis induced by oxaliplatin and 5-FU." (PMID 35205769, 2022). "Furthermore, another study has demonstrated that Fn may promote the nuclear translocation of β-catenin via a TLR4/P-PAK1 cascade in colorectal cancers." (PMID 33917384, 2021). "Therefore, this study aimed to clarify the prognostic roles of TLR2 and TLR4 in colorectal cancer." (PMID 32424768, 2020). "Modification of polysaccharide components present in apple changed the LPS/TLR4/NF-kB pathway; consequently, supplementation of apple polysaccharide significantly inhibited the migratory ability in vitro on the LPS/ TLR4/NF-kB pathway in colorectal cancer cells (HT-29 and SW620 cells)." (PMID 33105724, 2020). "F. nucleatum promotes colorectal cancer cell proliferation and tumorigenesis by activating Toll-like receptor 4(TLR4) signaling, which upregulates nuclear factor-κB, as indicated by increased MicroRNA-21 expression or the TLR4/p-PAK1/p-β-catenin S675-cascade signaling pathway." (PMID 31993418, 2019). "Furthermore, it has been observed that Anaerobic Peptostreptococcus activates Toll-like receptors 2 and 4 (TLR2 and TLR4), resulting in elevated intracellular reactive oxygen species (ROS) levels, which subsequently facilitate cell proliferation during the progression of colorectal cancer (CRC)." (PMID 39959156, 2025). "For instance, in colorectal cancer (CRC), palmitic acid upregulates TLR4 expression in CRC cells in a PU.1-dependent manner (where PU.1 binds to the TLR4 promoter)." (PMID 38523155, 2024). "This study is aimed at investigating the roles of Toll-like receptor 4 (TLR4) and microRNA-7 (miR-7) in colorectal cancer (CRC) development and progression." (PMID 38315263, 2024). "Recent studies have established a correlation between Fusobacterium nucleatum (Fn) and the occurrence and development of colorectal cancer (CRC), particularly noting that Fn infection upregulates BIRC3 in CRC cells via the TLR4/NF-κB pathway." (PMID 39301019, 2024).
colorectal cancer (continued). "In colorectal cancer models, it is known that tumor-secreted CTSK can bind to Toll-like receptor 4 (TLR4) on the surface of macrophages and promote M2 polarization through a mammalian target of rapamycin (mTOR)-dependent pathway." (PMID 38993570, 2024). "On the other hand, Gal-1 treatment induces EMT and increases cell invasion involving PI3K and TLR-4, while Gal-1 silencing decreases EMT-related cytokines and suppresses mesenchymal characteristics of LPS-activated colorectal cancer cell lines." (PMID 38570874, 2024). "For instance, baicalein, a novel toll-like receptor 4 (TLR4)-targeted therapeutic drug, inhibits the development of colorectal cancer (CRC) by inhibiting the TLR4/hypoxia-inducible factor-1/vascular endothelial growth factor signaling pathway." (PMID 37731740, 2023). "Toll-like receptor 4 (TLR4) is increasingly recognized for its ability to govern the etiology and prognostic outcomes of colorectal cancer (CRC) due to its profound immunomodulatory capacity." (PMID 35841426, 2023). "In immunocompetent mice bearing CT26 colorectal cancer cells, both oxaliplatin and cisplatin-induced immune response, but not when CRT was inhibited or depleted or when the toll-like receptor 4 (TLR4) was knocked out." (PMID 35806243, 2022). "LPS-induced toll-like receptor 4 (TLR4) signaling activates the integrin β1/PI3K/Akt axis, which enhances colorectal cancer cell adhesion and liver metastasis." (PMID 33406733, 2021). "Fusobacterium nucleatum targets TLR4 and MYD88 innate immune signaling and specific microRNAs to activate the autophagy pathway and alter the chemotherapeutic response in colorectal cancer." (PMID 33854588, 2021). "Another study discovered that in patients with colorectal cancer liver metastases, the expression of CXCR4 CXCR7, TLR2/TLR4, and PD-1/PD-L1 was significantly increased in metastatic liver tissues compared to unaffected liver tissues." (PMID 34568309, 2021). "LPS is a well-known inflammatory stimulus and has been reported to stimulate metastasis in human colorectal carcinoma cell lines (SW48) by increasing migration, adhesion, and invasion in a TLR4-dependent way." (PMID 32492880, 2020). "According to what had been founded in NCM460 and HCT116 cell lines, we suspected that in APC mutation population, ethanol was a risk factor for development of colorectal cancer, which might contribute to allowing gram-negative bacteria LPS into the blood, and activate TLR4/NF-κB signaling pathway." (PMID 26760960, 2016). "The expression levels of TLR2, TLR4, NF-κB and TNF-α in colorectal cancer and adenoma were also higher than those in the control tissues." (PMID 25435993, 2015). "Immunohistochemical analysis revealed that the expression of IE1–72, TLR2, TLR4, NF-κB and TNF-α protein in colorectal carcinoma was significantly higher than that in the normal tissues." (PMID 25435993, 2015). "Colorectal cancer tissues have higher TLR1, TLR2, TLR4 and TLR8 gene expression levels in general than do the normal colon mucosa from the same patient (p < 0.05)." (PMID 25547486, 2014). "Previous studies have reported that the Toll-like receptor family members TLR3, TLR4, and TLR5 were up-regulated in colorectal carcinoma tissues." (PMID 23866094, 2013). "The present study shows that exposure to LPS elevated CXC chemokine receptor 7 (CXCR7) expression in colorectal carcinoma SW480 and Colo 205 cell lines expressing TLR4/myeloid differential protein (MD-2)." (PMID 22180778, 2011). "Correlation of TLR4, MD-2, and CXCR7 expression with clinicopathologic features in colorectal carcinoma." (PMID 22180778, 2011). "We demonstrated that the recombination of TLR4, MD-2 and CXCR7 strongly correlated with tumor size, lymph node metastasis and distant metastasis in colorectal carcinoma tissue samples (p = 0.037, p = 0.002, p = 0.042, resp)." (PMID 22180778, 2011).
colorectal cancer (continued). "There was a statistically significant correlation between single TLR4, MD-2, and CXCR7 expression levels and human colorectal carcinoma TNM stage, advanced histological grade, tumor size and lymph node metastasis." (PMID 22180778, 2011). "The differences in expression of the three molecules (TLR4, MD-2 and CXCR7) between normal colorectal tissues and colorectal carcinoma tissues were all found to be statistically significant (p<0.001, p<0.001, p = 0.034, resp.)." (PMID 22180778, 2011). "Higher rates of TLR4 (53%), MD-2 (70%), and CXCR7 (29%) expression were found in colorectal carcinoma tissues than in normal tissues." (PMID 22180778, 2011). "Our studies suggest that exposure to LPS elevates CXCR7 expression in a colorectal carcinoma SW480 and Colo 205 cell lines expressing TLR4/MD-2." (PMID 22180778, 2011). "TLR4, MD-2 and CXCR7 exhibited mostly cytoplasmic and plasmalemmal staining in colorectal carcinoma tissues." (PMID 22180778, 2011). "To further substantiate the growth-promoting and pro-migration effects of CXCR7 mediated by TLR4, we investigated the clinicopathologic significance of TLR4, MD-2 and CXCR7 expression using immunohistochemistry in human colorectal carcinoma tissues." (PMID 22180778, 2011). "One such bacterium is Fusobacterium nucleatum which is associated with adverse prognosis and recurrence after chemotherapy (using 5-fluorouracil and oxaliplatin) for colorectal cancer (CRC), which influences molecules such as TLR4 and MYD88, and triggers microRNAs and autophagy mechanisms." (PMID 40927726, 2025). "Furthermore, their effective interaction with TLR-4 indicates their capability to trigger a comprehensive immune response, highlighting their potential as candidates for CTL-based immunotherapy in colorectal cancer." (PMID 40599850, 2025). "In colorectal carcinoma (CRC), exposure to LPS increases the expression of CXC chemokine receptor 7 (CXCR7) and enhances the proliferation and migration of SW480 and Colo 205 cells via the TLR4/myeloid differential protein (MD-2) pathway." (PMID 40444051, 2025). "In colorectal cancer, TLR2 expression may contribute to sporadic carcinogenesis and TLR4 may increase cancer cell survival." (PMID 38709790, 2024). "Fusobacterium nucleatum has been detected in both colorectal cancer tissues and fecal samples, influencing treatment responses by targeting Toll-like receptor 4 (TLR4) and MyD88 immune pathways and specific microRNAs to activate autophagy, thus serving as a biomarker for colorectal cancer." (PMID 39545038, 2024). "TLR4 is frequently upregulated in inflammatory bowel disease (IBD) and colorectal cancer (CRC)." (PMID 37576399, 2023). "In the colorectal cancer cell lines LOVO and SW480, PF increased caspase-dependent apoptotic cell death by regulating invasion, migration, proliferation, and colony formation and by inhibiting the TLR4/NF-kB axis and EGFL7." (PMID 38140352, 2023). "Moreover, Bmi-1 promote colorectal cancer migration and EMT in an inflammatory microenvironment by regulating TLR4/MD2/MyD88 complex-mediated NF-κB signaling pathway." (PMID 35897796, 2022). "Despite studies having reported that TLR4 is involved in the occurrence and development of liver cancer, lung cancer, gastric cancer, and colorectal cancer, the correlation of TLR4 and LSCC had not been explored." (PMID 34910689, 2021). "Instead of TLR2 or TLR4, BGN (which is significantly increased in colon cancer) may be a more useful marker in human colorectal cancer." (PMID 32050430, 2020). "In this current study, TLR4 blockade using neutralizing antibody alleviated HM-inhibited ERK phosphorylation, demonstrating that HM acts partially through TLR4 and suggesting the presence of other HM receptors in colorectal cancer cells." (PMID 32322173, 2020).
colorectal cancer (continued). "A recent study confirming downregulation of TLR4 and upregulation of TLR2 in colorectal carcinomas may partly explain these conflicts by indicating contrast effects of different TLRs on tumor pathogenesis." (PMID 31675995, 2019). "All these result suggested a critical role for LPS in migration, invasion, lymphangiogenesis and lymph node metastasis of colorectal cancer, providing evidence that LPS increased VEGF-C secretion to promote cell motility and lymphangiogenesis via TLR4- NF-κB/JNK signaling." (PMID 27713159, 2016). "Furthermore, the expression of IE1–72 in colorectal cancer tissues was found to correlate with TLR2 and TLR4, and the correlation coefficients were 0.515 and 0.462, respectively." (PMID 25435993, 2015). "Accordingly, simultaneous examination of the expression of TLR4, MD-2 and CXCR7 in cancer tissues of colorectal carcinoma may provide valuable prognostic diagnosis of carcinoma growth and metastasis." (PMID 22180778, 2011). "Similar observation was made in a variety of colorectal carcinoma cell lines where tumor cells expressed TLR4 but failed to coexpress CD14, an important auxiliary protein in the endotoxin receptor complex." (PMID 22110526, 2011). "Furthermore, higher rates of TLR4, MD-2, and CXCR7 expression were found in colorectal carcinoma tissues than in normal tissues." (PMID 22180778, 2011). "There were statistically significant differences in high expression of these single molecules, and high expression of two of the three molecules TLR4/MD-2, TLR4/CXCR7, TLR4/CXCR7 with regard to lymph node metastasis in patients with colorectal carcinoma (p<0.001, p<0.001, p = 0.001, resp)." (PMID 22180778, 2011). "At the same time, the incidence of lymph node metastasis tended to be higher in patients with colorectal carcinoma with high rather than low expression of TLR4, MD-2, or CXCR7 (p = 0.001, p = 0.012, p<0.001, resp.)." (PMID 22180778, 2011). "Interplay of TLR4, MD-2 and CXCR7 may be of interest in the context of novel immunomodulatory therapies for colorectal carcinoma." (PMID 22180778, 2011). "Notably, the present study suggests that TLR4, MD-2, and CXCR7 are highly expressed in colorectal carcinoma." (PMID 22180778, 2011). "The analysis of RT-PCR products showed that TLR4 and MD-2 were constitutively expressed in 4 out of 8 human colorectal carcinoma cell lines, including Colo 205, RKO, SW480 and SW620, whereas TLR4 and MD-2 were present respectively in only two cell lines such as DLD-1 and HCT-29." (PMID 22180778, 2011). "TLR4, IL-6 and TNF-α expression was upregulated by palmitic acid in a neuroblastoma cell line in vitro and in vivo, TLR4-/- colorectal cancer (CRC) tumor growth was not affected by a diet enriched with palmitic acid, while wild-type CRC tumor growth was increased upon dietary intervention in mice." (PMID 36830818, 2023). "In addition, the stemness of TLR4 positive colorectal cancer cells is stronger than TLR4 negative colorectal cancer cells." (PMID 36647071, 2023). "Using colorectal cancer cell lines (HCT116, DLD1, SW480, and HT-29) and xenograft mice, it was shown that F. nucleatum promotes colorectal cancer cell growth by modulating E-cadherin and promotes cancer cell proliferation via FadA adhesin, activating TLR4 signaling to nuclear factor-kB." (PMID 35283816, 2022). "To further corroborate this observation, we assessed the expression of TLR4 mRNA and the promoter methylation status of MLH1 in the healthy colonic mucosa of 63 patients who had colonoscopy for cancer screening or cancer follow up or who had colonic resection for colorectal cancer." (PMID 34026821, 2021). "Likewise, an anti-tumorigenic effect has also been suggested for the TLR4 agonist lipopolysaccharide (LPS; from Gram-negative bacteria) for the treatment of colorectal cancer and glioblastoma multiforme." (PMID 26863029, 2016).